ZNF217 (zinc finger protein 217)
Description:
Binds to the promoters of target genes and functions as repressor. Promotes cell proliferation and antagonizes cell death. Promotes phosphorylation of AKT1 at 'Ser-473'.
Synonyms: ZABC1
Tractability: Small molecule: a structure with a bound ligand is known. PROTAC: UniProt records ubiquitination sites on it; ubiquitination databases record sites on it.
Gene: Protein-coding gene on chromosome 20 (53,567,071 to 53,609,907, reverse strand). Ensembl gene ENSG00000171940.
Subcellular location: Nucleus
Subcellular location (Human Protein Atlas): Nuclear speckles; Mitochondria
Pathways (Reactome):
Cell-Cell communication: Negative Regulation of CDH1 Gene Transcription
Signal Transduction: Estrogen-dependent gene expression
Gene Ontology:
Molecular function: DNA-binding transcription repressor activity, RNA polymerase II-specific; protein binding; RNA polymerase II cis-regulatory region sequence-specific DNA binding; transcription cis-regulatory region binding; DNA-binding transcription factor activity; DNA-binding transcription factor activity, RNA polymerase II-specific
Biological process: negative regulation of DNA-templated transcription; negative regulation of transcription by RNA polymerase II; regulation of DNA-templated transcription; regulation of transcription by RNA polymerase II
Cellular component: histone deacetylase complex; nuclear speck; nucleoplasm; nucleus
Genetic constraint (gnomAD): Loss-of-function variants: 10 observed, 71.54 expected, observed/expected ratio (o/e) 0.14, 90% interval 0.085 to 0.24. The upper end of that interval is the gene's LOEUF score, 0.24, which puts it in group 1 of 6, group 1 being the genes least tolerant of losing a copy. Missense variants: 1,166 observed, 1,343.6 expected, observed/expected ratio (o/e) 0.87, 90% interval 0.83 to 0.91. Synonymous variants: 570 observed, 527.8 expected, observed/expected ratio (o/e) 1.08, 90% interval 1.01 to 1.16.
Homologues: Orthologues: chimpanzee ZNF217 (97% identical), macaque ZNF217 (96% identical), rabbit ZNF217 (76% identical), pig ZNF217 (75% identical), rat Zfp217 (71% identical), mouse Zfp217 (70% identical), dog ZNF217 (67% identical), guinea pig ZNF217 (60% identical), tropical clawed frog znf217 (37% identical), zebrafish znf217 (35% identical). Paralogues in human: ZNF536 (22% identical), ZNF516 (22% identical), ZNF219 (12% identical), SALL3 (11% identical), HIVEP1 (11% identical), SALL1 (11% identical), HIVEP3 (10% identical), HIVEP2 (10% identical), BCL11A (9% identical), SALL4 (9% identical), BCL11B (9% identical), RREB1 (9% identical), and 2 more.
Diseases named in the same sentence as ZNF217 in open-access papers:
ZNF217 is named in the same sentence as 70 diseases in open-access papers, as found by Europe PMC text mining. Sharing a sentence is not in itself a finding about the gene and the disease. The quoted sentences say what the papers report.
breast carcinoma (87 papers, 2003 to 2026). "High expression of zinc-finger protein 217 (ZNF217) in MDA-MB-231 breast cancer cells is associated with EMT and certain gene dysregulation." (PMID 38041134, 2023). "The high expression of ZNF217 was reported to be associated with the poor prognosis and the development of metastases in breast cancer." (PMID 36439454, 2022). "This study provides new insights into the possible role of the ZNF217-ΔE4 splice variant in breast cancer and suggests a close interplay between the ZNF217-WT and ZNF217-ΔE4 isoforms." (PMID 34277402, 2021). "The candidate oncogene ZNF217 has been recently proposed as a biomarker to assess the clinical response to NET in ER+ breast cancer, with high levels of ZNF217 associated with reduced responses to NET in a prospective study." (PMID 32690069, 2020). "Most interestingly, high ZNF217 expression levels confer resistance to ET in ER+ breast cancer cell lines, and ZNF217 expression silencing is associated with reversion of such resistance." (PMID 30740056, 2018). "Here, we aimed at investigating in a pilot prospective study the association between ZNF217 mRNA expression levels and the clinical response to neoadjuvant endocrine therapy (ET) in postmenopausal ER-positive (ER+) breast cancer patients." (PMID 30740056, 2018). "Here we report that exposure of breast cancer cells to hypoxia also induces ZNF217-dependent inhibition of m6A methylation of mRNAs encoding NANOG and KLF4, which is another pluripotency factor that mediates BCSC specification." (PMID 27590511, 2016). "These “repressed” genes include ESR1 (gene encoding ERα), ERBB2, GATA3, and ZNF217 —all critical genes to the etiology of breast cancer." (PMID 27539783, 2016). "The ZNF217 gene on human chromosome 20q13.2 encodes a transcription factor that is overexpressed in breast cancer." (PMID 27590511, 2016). "Zinc-figure protein 217 (ZNF217), a member of the Kruppel-like family of transcriptional factors, was firstly amplified in breast cancer and associated with aggressive tumor behavior and poor clinical prognosis." (PMID 27768596, 2016). "The Small cell fraction also showed copy number increases in six target genes (FGFR1, Myc, CCND1, HER2, TOP2A and ZNF217) associated with breast cancer." (PMID 26008969, 2015). "In an ER+ breast cancer context, high/positive ZNF217 expression levels thus seem to be associated with functional estrogen signaling." (PMID 26431164, 2015). "More importantly, the expression of lnc-ATB was significantly associated with ZEB1 and ZNF217 expression in TR breast cancer patients." (PMID 25871474, 2015). "ZNF217 has also been associated with aberrant response of endocrine therapy (a standard of care for ER+ breast cancers)." (PMID 26431164, 2015). "The 20q13 amplification including the ZNF217 gene coding for a transcription factor is found in ~ 20-30% of breast cancers and is associated with aggressive tumor behavior, shorter disease-free survival, chemoresistance, and poor prognosis." (PMID 24962896, 2014). "Data-mining of expression data from breast cancer patients also associates high ZNF217 expression with poor prognosis across multiple intrinsic subtypes and reduced response to hormone therapy." (PMID 24962896, 2014). "The putative transcription factor ZNF217 was identified within our predictive gene sets, and overexpression was associated with poor outcome in our breast cancer patients." (PMID 17428335, 2007). "Transcriptional enrichment analysis revealed that MRPS30‐DT might be associated the most with ZNF217 and FoxM1, whose roles in breast cancer have been demonstrated in the literature." (PMID 38886335, 2024). "Moreover, the levels of ZNF217 and miR-503 are associated with opposite outcomes in breast cancer patient cohorts, with high expression of ZNF217 associated with poor survival and high expression of miR-503 associated with improved survival." (PMID 27539783, 2016).
breast carcinoma (continued). "ZNF217-mediated paclitaxel resistance in breast cancer cells was associated with alterations in the intrinsic mitochondrial apoptosis pathway, through the deregulation of the balance between anti-apoptotic (Bcl-2 and Bcl-XL) and pro-apoptotic (Bad, Bak and Bax) proteins' expression." (PMID 26431164, 2015). "More precisely, ZNF217 might interfere with the lysophosphatidylcholine acyltransferase 1 recently implicated in breast cancer progression and metastatic dissemination." (PMID 26431164, 2015). "RTQ-PCR investigation in several primary breast cancer cohorts found that high ZNF217 mRNA levels were associated with shorter relapse-free survival (RFS) (univariate analysis, p = 0.003, p = 0.017 and p = 0.02; p = 0.015) and with the development of metastases (p = 0.002, p = 0.0008 and p = 0.025)." (PMID 26431164, 2015). "Knockdown of ZNF217 followed by expression profiling identified 3,402 differentially affected genes suggesting a functional regulatory role linked to multiple signaling pathways associated with breast cancer." (PMID 24962896, 2014). "Two palindrome candidates, 17q23.2 (Chr17: 56,691,822-56,700,625) and 20q13.2 (Chr20: 52,771,235-52,783,881), contained the BCAS3 and ZNF217 genes that was amplified and overexpressed in breast cancers and was often associated with chromosomal alterations affecting the locus." (PMID 24885769, 2014). "Transcriptome profiling following ZNF217 depletion identifies differentially expressed genes co-bound by ZNF217 and ERalpha; gene ontology suggests a role for ZNF217-ERalpha in expression programs associated with ER+ breast cancer studies found in the Molecular Signature Database." (PMID 24962896, 2014). "Interestingly, in addition to ZNF217, we observed that high levels of expression of several genes from the 20q13 region were associated with poor prognosis in the breast cancer patients." (PMID 17428335, 2007). "used RT-qPCR to detect ZNF217 mRNA expression in 113 breast cancer samples and found that high expression of ZNF217 is associated with a higher risk of isolated bone metastasis in ER+ patients, but the level of ZNF217 cannot predict metastasis in other subtypes of breast cancer." (PMID 38041134, 2023). "The rs1056948 single nucleotide polymorphisms (SNP) in the 3′ UTR of ZNF217 (with a putative function in inactivating exonic splicing enhancer sequences) and the rs61730988 SNP (responsible for the E914D mutation) are associated with breast cancer susceptibility." (PMID 26431164, 2015). "CRISPR/Cas9-mediated silencing of the ZNF217 gene in MDA-MB-231 breast cancer cells impairs cell aggressiveness, while reintroduction of the ZNF217-ΔE4 isoform is sufficient to restore increased cell proliferation, migration, invasion, and stemness features." (PMID 41749916, 2026). "In breast cancer cells ZNF217 induces ErbB3 expression, leading to an increase in PI-3/Akt signaling." (PMID 41345234, 2025). "Studies have demonstrated that ZNF217 acts as an oncogene in breast cancer cell lines by promoting cell proliferation, invasiveness, and chemotherapy resistance." (PMID 38886335, 2024). "A previous study demonstrated that depletion of ZNF217 reduced the basal phosphorylation of AKT in breast cancer cells." (PMID 38067329, 2023). "That study also illustrated that triciribine ameliorated the chemo-resistance of doxorubicin in breast cancer cells overexpressing ZNF217." (PMID 38067329, 2023). "As expected, the top enriched pathways are genes in amplified regions previously identified from breast cancer, such as genes like ZNF217 and BCAS3 in MCF7; a selected list of luminal genes have also been enriched in the luminal cell lines MCF7 and T47D." (PMID 36153537, 2022). "In future work, it would thus be of great interest to investigate the expression levels of both ZNF217-ΔE4 and ZNF217-WT as well as the DNA methylation status of the ZNF217 gene in breast cancer tissues from patients." (PMID 34277402, 2021).
breast carcinoma (continued). "The first key finding of our study was the identification of ZNF217-ΔE4 mRNA in primary breast tumors, indicating that the exon 4-skipping process of the ZNF217 pre-mRNA occurs in breast cancer." (PMID 34277402, 2021). "We have previously reported that high mRNA levels of ZNF217 are of poor prognosis and represent an early indicator of relapse in breast cancer, with the most powerful prognostic value observed in Luminal subtypes." (PMID 34277402, 2021). "Our previous work contributed to the demonstration that breast cancer cells possessing high ZNF217 expression levels display a more aggressive phenotype (e.g. increased cell proliferation, increased invasive properties and resistance to chemotherapy)." (PMID 34277402, 2021). "With the aim to study the impact of ZNF217-ΔE4 expression on breast cancer cells phenotype, we established stable MDA-MB-231 cells constitutively overexpressing the ZNF217-ΔE4 protein." (PMID 34277402, 2021). "We thus propose a model where the ZNF217-ΔE4 isoform plays a biologically relevant role in breast cancer, at least by impacting epigenetic-driven mechanisms governing the expression of ZNF217-WT." (PMID 34277402, 2021). "Again, both ZNF217-WT (E3-E4) and ZNF217-ΔE4 (E3-E5) isoforms display significant mRNA expression differences between the breast cancer molecular subtypes (p = 0.007 and p = 0.056, respectively, Kruskal-Wallis Test, data not shown)." (PMID 34277402, 2021). "Considering the key role of the ZNF217 oncogene in breast cancer and its strong biomarker value, the ZNF217-ΔE4 transcript is thus of utmost interest." (PMID 34277402, 2021). "We next sought to explore the clinical and functional relevance of ZNF217-ΔE4 expression in breast cancer." (PMID 34277402, 2021). "Our analysis further discovered spliced alignments from exon 3 to exon 5 (exon 4-skipping, E3-E5), revealing the expression of the ZNF217-ΔE4 isoform in primary breast cancers." (PMID 34277402, 2021). "The expressions of hypoxia-induced pluripotent factors and ALKBH5 or ZNF217 in breast cancer cell lines are dependent on HIF." (PMID 34745269, 2021). "Ectopic overexpression of ZNF217-ΔE4 in breast cancer cells promoted an aggressive phenotype and an increase in ZNF217-WT expression levels that was inversely correlated with DNA methylation of the ZNF217 gene." (PMID 34277402, 2021). "Our results demonstrate that CESC patients with high NUSAP1 expression were enriched in the G2M checkpoint, MYC targets, and breast cancer ZNF217, which are closely related to the early onset of cancer and the risk of tumor progression and metastasis." (PMID 32226503, 2020). "In breast cancer, ZNF217 has been found to be essential for DNA hypermethylation of p15ink4b and does so by recruiting the CoREST complex to the promoter region." (PMID 32051553, 2020). "GSEA demonstrated that CESC patients with high expression of NUSAP1 were enriched in the G2M checkpoint, MYC targets, and breast cancer ZNF217." (PMID 32226503, 2020). "Particularly, copy number loss of ZNF217 was associated with shorter OS, DFS and PFS of breast cancer patients." (PMID 33585234, 2020). "We observed that G2M checkpoint, MYC target V2, and breast cancer ZNF217 were differentially enriched in the high NUSAP1 expression phenotype." (PMID 32226503, 2020). "In this well-described and well-characterized in vivo model, mice injected with ZNF217-positive breast cancer cells developed osteolytic lesions validated by microCT, and only in extremely rare cases were concomitant metastases at other locations observed." (PMID 31275146, 2019). "A study showed that hypoxia was related to increased breast cancer stem cell formation directly through upregulating ALKBH5 or indirectly through ZNF217/METTL3-METTL14-complex pathway." (PMID 30877265, 2019). "The impact was significantly greater with ZNF217-positive breast cancer cells displaying aggressiveness and with the ability to develop severe osteolytic lesions." (PMID 31275146, 2019).
breast carcinoma (continued). "We previously reported that in breast cancer cells, the ZNF217 oncogene drives BMP pathway activation, increases the metastatic growth rate in the bone, and accelerates the development of severe osteolytic lesions in mice." (PMID 31275146, 2019). "ZNF217 has been reported to be a marker of poor prognosis in breast cancer that drives epithelial-mesenchymal transition and invasion by recruiting EZH2 to its target genes, which are marked with an H3K27me3 enrichment peak." (PMID 30764831, 2019). "In mice, experiments conducted by intracardiac injection of ZNF217-positive breast cancer cells revealed that these latter rapidly colonize the bone, leading to the development of severe multiple BM detectable as early as 7 days post-injection." (PMID 31275146, 2019). "A series of in vitro experiments showed that BMP signaling is strongly involved in ZNF217-mediated breast cancer cell aggressiveness." (PMID 31275146, 2019). "We previously reported that ectopic expression of the ZNF217 oncogene in MDA-MB-231 breast cancer cells leads to the constitutive activation of the BMP pathway, indicating that ZNF217 is a novel upstream BMP signaling activator." (PMID 31275146, 2019). "Recently, it was reported that a HIF-regulated decrease in m6A through an increase in ALKBH5 and/or ZNF217 expression maintains pluripotency of breast cancer stem cells in several established breast cancer cell lines." (PMID 30131850, 2018). "One such example is ZNF217, which is hit in an associated RAD21 binding site by eight breast cancer mutations and by four in other cancer types." (PMID 29354286, 2018). "Nevertheless, we found that ZNF217 expression levels are predictive of neoadjuvant ET response in ER+ breast cancer." (PMID 30740056, 2018). "Altogether, these data support the idea that in the luminal breast cancer subclass, ZNF217 expression levels relate to ET response and provide a novel candidate biomarker." (PMID 30740056, 2018). "The aim of this pilot study is to investigate the predictive value of ZNF217 mRNA levels for response to neoadjuvant ET in patients with ER+ breast cancer." (PMID 30740056, 2018). "These pre-clinical data support results observed in breast cancer patients, namely that increased expression of ZNF217 imparts resistance to standard treatments used for breast cancer." (PMID 29312549, 2017). "ZNF217 was first characterized as the ‘driver’ oncogene amplified at 20q13.2 in breast cancer, where it was found to promote cellular immortalization." (PMID 28212443, 2017). "In particular, ZNF217, which is located on 20q13 near the locus that encodes RAE1, was previously reported as a novel breast cancer gene along with EGFR1, ERBB2, and PPMID26." (PMID 28181567, 2017). "ZNF217 is a Krüppel-like zinc finger protein amplified and overexpressed in ∼25% of breast cancer patients and is a biomarker of poor prognosis." (PMID 29312549, 2017). "We previously identified the transcription factor ZNF217 (human) / Zfp217 (mouse) as an oncogene and prognostic indicator of reduced survival, increased metastasis, and reduced response to therapy in breast cancer patients." (PMID 29312549, 2017). "ZNF217 is required for and promotes increased activation of Akt, which also plays a critical role in promoting chemotherapy resistance in breast cancer cells." (PMID 29312549, 2017). "We previously identified ZNF217 (human)/Zfp217 (mouse) as a candidate therapeutic target with prognostic value for resistance to breast cancer therapies." (PMID 29312549, 2017). "Previous study showed that ZNF217 and ERα proteins bound to each other in breast cancer cells while ERα positively regulated the expression of VEGF5." (PMID 28607476, 2017). "Deregulated methylation status at the ZNF217 gene promoter has been observed in glioblastoma and breast cancer." (PMID 27768596, 2016). "We have also analyzed the effect of ALKBH5 or ZNF217 loss of function on the BCSC phenotype and breast cancer metastasis." (PMID 27590511, 2016).